KRTAP4-6 (keratin associated protein 4-6)
Description:
In the hair cortex, hair keratin intermediate filaments are embedded in an interfilamentous matrix, consisting of hair keratin-associated proteins (KRTAP), which are essential for the formation of a rigid and resistant hair shaft through their extensive disulfide bond cross-linking with abundant cysteine residues of hair keratins. The matrix proteins include the high-sulfur and high-glycine-tyrosine keratins.
Synonyms: KAP4.15; KRTAP4-15; KRTAP4.15; KAP4.6
Tractability: No criterion of Open Targets' tractability assessment is met for any kind of drug.
Gene: Protein-coding gene on chromosome 17 (41,139,433 to 41,140,544, reverse strand). Ensembl gene ENSG00000198090.
Pathways (Reactome):
Developmental Biology: Keratinization
Gene Ontology:
Cellular component: cytosol; keratin filament
Genetic constraint (gnomAD): Loss-of-function variants: 2 observed, 3.24 expected, observed/expected ratio (o/e) 0.62, 90% interval 0.25 to 1.68. That is too few expected variants to judge how well the gene tolerates losing a copy. Missense variants: 275 observed, 259.85 expected, observed/expected ratio (o/e) 1.06, 90% interval 0.96 to 1.17. Synonymous variants: 97 observed, 86.31 expected, observed/expected ratio (o/e) 1.12, 90% interval 0.95 to 1.33.
Homologues: Orthologues: chimpanzee KRTAP4-6 (95% identical), mouse Krtap4-7 (64% identical), mouse Krtap4-24 (61% identical), rat Krtap9-7 (51% identical). Paralogues in human: KRTAP4-12 (91% identical), KRTAP4-9 (80% identical), KRTAP4-11 (77% identical), KRTAP4-8 (75% identical), KRTAP4-5 (72% identical), KRTAP4-7 (66% identical), KRTAP4-3 (62% identical), KRTAP4-4 (59% identical), KRTAP4-2 (52% identical), KRTAP4-1 (48% identical), KRTAP10-7 (46% identical), KRTAP10-4 (44% identical), and 35 more.